HCN2 (hyperpolarization activated cyclic nucleotide gated potassium and sodium channel 2)
Diseases named in the same sentence as HCN2 in open-access papers (continued):
Sharing a sentence is not in itself a finding about the gene and the disease.
peripheral nerve injury (2 papers, 2023 to 2026). Injury to a peripheral nerve. "Collectively, these findings suggest that CCI-induced alterations in cAMP-PKA-pCREB signaling promote HCN2 accumulation in injured axons, thereby contributing to the development of orofacial neuropathic pain following peripheral nerve injury." (PMID 41607332, 2026). "In conclusion, the present study demonstrates that HCN2 plays a crucial role in the TC neuronal hyperexcitability, which in turn, activates VPL–S1HL excitatory synaptic transmission and promotes neuropathic pain behavior after peripheral nerve injury." (PMID 36538279, 2023).
schizophrenia (2 papers, 2014 to 2025). A major psychotic disorder characterized by abnormalities in the perception or expression of reality. "The only genes observed as significant in both differential expression and accessibility analysis, specifically when examining genetic risk, are INO80E and HCN2 in excitatory neurons’ layers 2/3 for schizophrenia." (PMID 40053590, 2025). "Notably, INO80E and HCN2 genes exhibited dysregulation in excitatory neurons’ superficial layers 2/3 influenced by schizophrenia polygenic risk." (PMID 40053590, 2025). "Genomic tracks surrounding HCN2 and INO80E illustrate different ATAC coverage for the high– and low–schizophrenia risk groups." (PMID 40053590, 2025).
temporal lobe epilepsies (2 papers, 2022). "Several phosphosites for HCN1 and HCN2 have been mapped in chronic epilepsy cases and animal models of temporal lobe epilepsy." (PMID 35663267, 2022). "The disruption of Ih current disturbs hippocampal theta function in rat models of temporal lobe epilepsy, and during seizures, there is a reduced expression of HCN1 channel and upregulation of HCN2 channel." (PMID 35663267, 2022).
triple-negative breast carcinoma (2 papers, 2022 to 2025). An invasive breast carcinoma which is negative for expression of estrogen receptor (ER), progesterone receptor (PR), and human epidermal growth factor receptor 2 (HER2). "Interestingly, recent data indicate that HCN2 is overexpressed in triple negative breast cancer cells and that its inhibition or depletion leads to misregulation of intracellular Ca2+ regulation and ER stress." (PMID 39663000, 2025). "Studies have found that HCN2 showed the most significant upregulation in the HER2-positive and triple-negative breast cancer (TNBC) cell lines as compared to ER-positive breast cancer cell lines." (PMID 36304471, 2022).
Ventricular arrhythmia (2 papers, 2015 to 2019). "We next examined whether hypokalemia could induce ventricular arrhythmia in HCN2-Tg mice in vivo." (PMID 31087220, 2019). "These mice died of sudden arrhythmia aged eight weeks, indicating that HCN2 and HCN4 overexpression in the ventricles may contribute to ventricular arrhythmias." (PMID 26005035, 2015).
Alzheimer disease (1 paper, 2025). A progressive, neurodegenerative disease characterized by loss of function and death of nerve cells in several areas of the brain leading to loss of cognitive function such as memory and language. "The novel oxo-palmatine derivative 2q targets hyperpolarization-activated cyclic nucleotide-gated channel 2 (HCN2) to reduce Aβ deposition and Tau protein phosphorylation, thereby improving Alzheimer’s disease pathological features." (PMID 40786032, 2025).
amyotrophic lateral sclerosis 8 (1 paper, 2018). "Here we show that vesicle-associated membrane protein–associated protein B (VAPB), previously associated with a familial form of amyotrophic lateral sclerosis 8, is an essential HCN1 and HCN2 modulator." (PMID 29879376, 2018).
atrial fibrillation (1 paper, 2015). A disorder characterized by an electrocardiographic finding of a supraventricular arrhythmia characterized by the replacement of consistent P waves by rapid oscillations or fibrillatory waves that vary in size, shape and timing and are accompanied by an irregular ventricular response. "Compared with aged patients with sinus rhythm, aged patients with atrial fibrillation exhibited significantly higher HCN2 and HCN4 channel mRNA and protein expression levels (P<0.05), but significantly lower expression levels of miR-1 and miR-133 (P<0.05)." (PMID 26005035, 2015). "In patients with aged atrial fibrillation, the expression of HCN2 and HCN4 channels was enhanced compared with aged and adult sinoatrial fibrillation patients, whereas expression levels of miR-1 and miR-133 were lower." (PMID 26005035, 2015). "Expression levels of HCN2 and HCN4 increased with age, and a greater increase was identified in patients with age-associated atrial fibrillation compared with that in those with aged sinus rhythm." (PMID 26005035, 2015). "Similarly, the aged atrial fibrillation group exhibited significantly enhanced HCN2 and HCN4 protein expression levels compared to those of the aged sinus rhythm group (P<0.05; HCN2, 1.04±0.19 vs. 0.92±0.12; HCN4, 1.12±0.11 vs. 1.02±0.08)." (PMID 26005035, 2015). "It was therefore suggested that this age-associated increase in HCN2 and HCN4 expression enhanced the If current and therefore may increase the incidence of ventricular premature beats and atrial tachycardia, triggering atrial fibrillation." (PMID 26005035, 2015). "It was hypothesized that age-dependent changes in HCN2, HCN4, miR-1 and miR-133 expression may contribute to age-associated atrial fibrillation, and therefore the correlation between expression levels, among adult (≤65 years) and aged patients (≥65 years), and sinus rhythm was determined." (PMID 26005035, 2015). "Compared with the aged sinus rhythm group, the aged atrial fibrillation group also exhibited significantly enhanced levels of HCN2 and HCN4 mRNA expression (P<0.05; HCN2, 1.00±0.08 vs. 0.49±0.07; HCN4, 1.05±0.23 vs. 0.53±0.09)." (PMID 26005035, 2015).
bipolar disorder (1 paper, 2025). A disorder of the brain that causes unusual shifts in mood, energy, activity levels and the ability to carry out day-to-day tasks. "Only with the network approach, HCN2’s gene scores in Exc_L2-3 were positively correlated with bipolar disorder PRS, and its expression in Exc_L2-3 showed positive correlations with other excitatory neuron populations but negative correlations with VIP and SST interneurons (In_VIP and In_SST)." (PMID 40053590, 2025).
bladder cancer (1 paper, 2026). "Functionally, HCN2 knockdown in bladder cancer impeded cell proliferation, induced apoptosis, and curtailed migration and invasion." (PMID 42074076, 2026). "We employed bioinformatics analysis and immunohistochemistry to assess the role of HCN2 in bladder cancer, integrating in vitro and in vivo models to evaluate the impact of HCN2 on cell behavior." (PMID 42074076, 2026). "Our investigation revealed a significant upregulation of HCN2 in bladder cancer tissues, which was predictive of a poorer clinical outcome." (PMID 42074076, 2026). "This study uncovers the novel mechanism by which HCN2 regulates ferroptosis via the REST-BGN axis, affecting bladder cancer cell behavior, and provides new perspectives and strategies for future clinical treatment." (PMID 42074076, 2026).
channelopathy (1 paper, 2024). Channelopathies are a group of diseases caused by the dysfunction of ion channel subunits or their interacting proteins. "In this study, we identified a significant relationship between the HCN channelopathy, especially the HCN2 channelopathy, and the hyperactivation of LHb neurons." (PMID 38961317, 2024).
cocaine addiction (1 paper, 2024). "Cocaine addiction can increase the expression of HCN channels in prefrontal cortex, VTA, and other brain regions, while another study pointed out that the expression of HCN2 and HCN4 channels in VTA were downregulated after cocaine addiction." (PMID 39267158, 2024).
diabetes (1 paper, 2021). "The expressions of HCN2 in left and right atria after 6 weeks of diabetes were unaltered as compared to controls." (PMID 33653265, 2021). "Consequently, our results underline the fact, that observed HCN2 downregulation in diabetes is highly specific for ventricular myocytes and it is not observed in either atrial tissue or H9c2 cells." (PMID 33653265, 2021).
diabetic cardiomyopathy (1 paper, 2021). Diabetic cardiomyopathy is a disorder of the heart muscle in people with diabetes. "We focused on miR-1 and miR-133a as their dysregulation contributes to diabetic cardiomyopathy and moreover, also influences HCN2 and HCN4 expressions." (PMID 33653265, 2021).
dilated cardiomyopathy (1 paper, 2021). Cardiomyopathy which is characterized by dilation and contractile dysfunction of the left and right ventricles. "HCN channels have been shown to play a role in the arrhythmogenesis of dilated cardiomyopathy, and HCN2-overexpressing hearts have increased VT susceptibility." (PMID 34489488, 2021).
Dystonia (1 paper, 2025). An abnormally increased muscular tone that causes fixed abnormal postures. "HCN2 variants phenotypic spectrum also include dystonia and movement disorders, which have not been yet reported in individuals with HCN2 or HCN1 variants." (PMID 40468825, 2025).
epileptic syndromes (1 paper, 2022). "Similar to HCN1 gene, some of the variants are related to different epileptic syndromes which suggest heterogeneity of the HCN2 phenotypes." (PMID 35663267, 2022).
hyperglycaemia (1 paper, 2021). "Excess of glucose did not result in HCN channels expression changes in H9c2 cells indicating that hyperglycaemia per se is not sufficient to downregulate HCN2." (PMID 33653265, 2021). "We hypothesized that myocardial alterations in HCN2 and HCN4 channels occur under hyperglycaemia." (PMID 33653265, 2021).
hyperthyroidism (1 paper, 2023). Overactivity of the thyroid gland resulting in overproduction of thyroid hormone and increased metabolic rate. "At the molecular level, such resistance occurs despite expected upregulation of Hcn2 and Hcn4, indicating that these classical T3 target genes alone are not sufficient to mediate the tachycardia of hyperthyroidism." (PMID 37286550, 2023).
Hypokalemia (1 paper, 2019). An abnormally decreased potassium concentration in the blood. "We conclude that in hypokalemia in our mice model, the HCN2 channel was constitutively activated at the hyperpolarized RMP, thereby destabilizing the electrophysiological activity of ventricular myocytes." (PMID 31087220, 2019). "In the present study, our aim was to examine the effects of hypokalemia on the ventricular myocytes isolated from HCN2-Tg mice." (PMID 31087220, 2019). "We have examined the effect of hypokalemia in the myocytes of transgenic mice overexpressing the hyperpolarization-activated, cyclic nucleotide-sensitive (HCN) channel in the heart (HCN2-Tg mice)." (PMID 31087220, 2019).
hypopituitarism (1 paper, 2018). A condition of diminution or cessation of secretion of one or more hormones from the anterior pituitary gland. "An elevation in both these hormones is inconsistent with hypopituitarism due to loss of HCN2 expression." (PMID 29466436, 2018).
ileus (1 paper, 2023). Decrease in peristalsis in the absence of a mechanical bowel obstruction. "As macrophages play a significant role in the development of ileus, we also examined the expression of HCN2 in macrophages." (PMID 37298834, 2023). "In a rodent model of ileus, HCN2 was significantly down-regulated in intestinal smooth muscle compared to controls." (PMID 37298834, 2023). "We found that HCN2 is down-regulated in intestinal smooth muscle in an ileus model." (PMID 37298834, 2023). "Based on a previous microarray study showing that HCN2 expression was decreased in intestinal smooth muscle when ileus was induced, we speculated that the attenuated effects of HCN inhibition after increased stretch were due to the down-regulation of HCN2." (PMID 37298834, 2023). "Overall, our results suggest that decreased HCN2 expression induced by mechanical signals, such as intestinal wall distension or edema development, may contribute to the development of ileus." (PMID 37298834, 2023). "In addition, macrophages play a significant role in the development of ileus; thus, we also determined if HCN2 expression changed in macrophages in response to stretch." (PMID 37298834, 2023). "HCN2 is down-regulated in intestinal smooth muscle in a rodent model of ileus." (PMID 37298834, 2023). "Overall, our results suggest that decreased HCN2 expression induced by mechanical signals may contribute to the development of ileus." (PMID 37298834, 2023).
motor neuron disease (1 paper, 2018). "A major question arising from our results is whether this novel function of VAPB in regulating HCN1 and HCN2 activities could be involved in motor neuron disease." (PMID 29879376, 2018).
myocardial disease (1 paper, 2015). "A dnNRSF-expressing transgenic mouse model with gradually progressive myocardial disease was demonstrated to overexpress HCN2 and HCN4 in the ventricle." (PMID 26005035, 2015).
overactive bladder (1 paper, 2013). Symptom of overactive detrusor muscle of the urinary bladder that contracts with abnormally high frequency and urgency. "Compared with the normal control rats, HCN2 mRNA and protein expression within the bladder were upregulated and were reversed by electroacupuncture in overactive bladder rats as determined by RT-PCR, western blotting and immunohistochemistry." (PMID 24194780, 2013).
pituitary tumor (1 paper, 2022). A benign or malignant neoplasm affecting the pituitary gland. "HCN2, HCN3, or mixed HCN2 + HCN3 channels were reported previously to be distributed in pituitary tumor (GH3) cells." (PMID 35806190, 2022).
Stroke (1 paper, 2013). Sudden impairment of blood flow to a part of the brain due to occlusion or rupture of an artery to the brain. "Hcn2+/+ animals showed stroke volumes of 36.2 ± 19.3 mm3 while hcn2-/- mice displayed infarct areas of 40.5 ± 25.2 mm3 (n = 11 per group; p = 0.66)." (PMID 24373160, 2013). "Here, we test the hypothesis that functional HCN2 channels limit the infarct volumes and improve neurological and motor abilities in a mouse model of stroke (tMCAO)." (PMID 24373160, 2013). "Thus, we here tested whether HCN2 ablation would interfere with the stability of the membrane potential and thereby influence stroke pathophysiology." (PMID 24373160, 2013). "Although hcn2 gene expression was found to be reduced in infarcted basal ganglia 24 h after occlusion, it is concluded that with the techniques applied in this study an impact of HCN2 channels on stroke development in mice could not be determined." (PMID 24373160, 2013). "However, together with a former study on TASK3 these results implicate that both TASK3 and HCN2 which were supposed to be neuroprotective due to their pH-dependency, do not influence ischemic neurodegeneration during stroke in the tMCAO model." (PMID 24373160, 2013). "Here, we hypothesized that the absence of HCN2, an important functional counter player of TASK channels, affects neuronal survival during stroke-induced tissue damage." (PMID 24373160, 2013).
Tinnitus (1 paper, 2015). Tinnitus is an auditory perception that can be described as the experience of sound, in the ear or in the head, in the absence of external acoustic stimulation. "Therefore, we propose that manipulations that reduce HCN2 channel activity may serve as potential therapeutic path for preventing the development of tinnitus." (PMID 26312501, 2015).
transient cerebral ischemia (1 paper, 2013). "Here, we tested whether transient cerebral ischemia influenced hcn2 expression levels." (PMID 24373160, 2013).
Tremor (1 paper, 2017). An unintentional, oscillating to-and-fro muscle movement about a joint axis. "Upon HCN2 knockout, mice are hypoactive, show a wide-based and abnormal gait, and exhibit a tremor." (PMID 28286469, 2017).
Virus infection (1 paper, 2023). "Virus infection was confirmed through the restricted expression of GFP in vCA1, accompanied by reduced HCN2 protein expression (p = 0.032, control vs. down)." (PMID 37762124, 2023). "Four weeks after the shRNA virus infection, we found a significant increase in the count of c-Fos-positive neurons co-labeled with CamkII-GFP-shRNA-HCN2 compared with the control group (c-Fos+/GFP-CamkII+) (p < 0.001), indicating strong inhibition of vCA1 pyramidal neurons with HCN2 knockdown." (PMID 37762124, 2023).
cancer (3 papers, 2021 to 2025). A tumor composed of atypical neoplastic, often pleomorphic cells that invade other tissues. "Since normal breast cells have low HCN2/3 expression, these results indicate that the effect of both IVA and OLA are cancer cell-specific, and co-treatment has a more pronounced impact on cells that highly express HCN2/3." (PMID 40764992, 2025). "HCN2 has been shown to be expressed in non‐small‐cell lung carcinoma, and patch‐clamp experiments showed hyperpolarization of the cancer cells on exposure to proapoptotic trigger." (PMID 34841695, 2021). "Therefore, the future effort can be made to develop a drug that recognizes explicitly HCN2 and HCN3 only, which would be expected to be more cancer‐specific than Ivabradine." (PMID 34841695, 2021).
Tumor (3 papers, 2021 to 2026). "We also validated significantly upregulated expression of ER‐stress markers GRP78, ATF4, CHOP and apoptosis marker BIP, BIM, cleaved caspase 3 in the tumour xenografts with HCN2 or HCN3 knockdown." (PMID 34841695, 2021). "Similarly, depletion of HCN2 or HCN3 by shRNA could significantly reduce the growth rate of the tumours in vivo." (PMID 34841695, 2021). "Consistently in the xenograft model, a low dose of Ivabradine (1 mg/kg) or paclitaxel (2 mg/kg) alone, given twice weekly, did not affect tumour volume or did not affect the expression of HCN2 and HCN3." (PMID 34841695, 2021).
movement disorder (1 paper, 2025). Neurological conditions resulting in abnormal voluntary or involuntary movement, which may impact the speed, fluency, quality and ease of movement. "Another difference between HCN1 and HCN2 variants is the lack of movement disorders reported so far for individuals with the HCN1 variants." (PMID 40468825, 2025).
HCN2 also shares sentences with these, for which no sentence is quoted: generalized epilepsy (5 papers); cardiac arrhythmias (2); neurological diseases (2); Nociceptive (2); Ventricular hypertrophy (2); alcohol use disorder (1); asthenia (1); atrial tachycardia (1); autism (1); breast tumour (1); cardiomyopathy (1); cardiovascular disease (1); colorectal cancer (1); cortical dysplasia (1); delirium (1); febrile seizures (1); genetic epilepsy with febrile seizure plus (1); genetic generalized epilepsy (1); infection (1); Infertility (1); injury (1); memory impairment (1); migraine with aura (1); myocardial infarction (1); neurodevelopmental disorder (1); neuropathic pain (1); non-small cell lung carcinoma (1); Onset (1); thyrotoxicosis (1); tonic-clonic seizures (1).
A further 4 diseases each share a sentence with HCN2 in 1 paper.